RN7SKP220 (RN7SK pseudogene 220)
Gene: Miscellaneous RNA gene on chromosome 10 (25,393,557 to 25,393,844, reverse strand). Ensembl gene ENSG00000222543.
Homologues: Orthologues: chimpanzee 7SK (99% identical), guinea pig 7SK (59% identical), mouse Gm56334 (59% identical), guinea pig 7SK (58% identical), mouse Gm55120 (57% identical), mouse Gm55655 (51% identical). Paralogues in human: RN7SKP33 (72% identical), RN7SKP37 (72% identical), RN7SKP77 (71% identical), RN7SKP45 (71% identical), RN7SKP102 (70% identical), RN7SKP217 (70% identical), RN7SKP224 (70% identical), RN7SKP294 (70% identical), RN7SKP103 (70% identical), RN7SKP130 (70% identical), RN7SKP211 (70% identical), RN7SKP173 (69% identical), and 284 more.